ENSG00000298117 (novel transcript)
Gene: Long non-coding RNA gene on chromosome 8 (66,112,236 to 66,114,226, reverse strand). Ensembl gene ENSG00000298117.
Gene Ontology:
Molecular function: triplet codon-amino acid adaptor activity
Biological process: translation